IL17C (interleukin 17C)
Diseases named in the same sentence as IL17C in open-access papers (continued):
Sharing a sentence is not in itself a finding about the gene and the disease.
Arthritis (4 papers, 2015 to 2024). Inflammation of a joint. "In addition, IL-17C was implicated in pathogenic responses in the joints, leading to the exacerbation of arthritis induced by collagen in the mouse." (PMID 30127781, 2018). "Since IL-17C also participates in joint damage in mouse models of arthritis, it remains to be addressed whether its inhibition could be advantageous." (PMID 30127781, 2018).
inflammatory skin disease (4 papers, 2022 to 2025). Inflammatory skin disorders covers a broad category that includes many conditions ranging in severity, from mild itching to grave medical health complications These disorders are common in people of all ages and races. "However, the therapeutic potential of blocking IL-17C for inflammatory skin diseases has not been fully explored." (PMID 38470486, 2024).
Autoimmunity (3 papers, 2017 to 2022). The occurrence of an immune reaction against the organism's own cells or tissues. "IL17C expression in the gut epithelium has also been linked to autoimmunity and tumorigenesis." (PMID 28447937, 2017). "Herein, the discussion is focused on IL-17A, IL-17C and IL-17F, since these families mediate autoimmunity the best, albeit in the presence of other additional families." (PMID 35203707, 2022). "Nevertheless, in regard to autoimmunity and chronic inflammatory diseases, IL-17A, IL-17C and IL-17F act as the key mediators in manipulating the pathway cellular machinery." (PMID 35203707, 2022). "Thus, it might be possible that the protective role that IL-17C plays for the integrity of epithelial barrier function exceeds its pathological effect for TH17 stimulation in autoimmunity." (PMID 32174926, 2020).
candidiasis (3 papers, 2015 to 2024). Infection with the organism Candida. "At odds with IL-17A that controls fungal proliferation and infection, and whose blockage has been associated with fungal overgrowth and candidiasis, IL-17C is dispensable for immunity against candidiasis." (PMID 33244315, 2020). "As shown, there was no apparent role for IL-17C or IL-17RE signaling in host defense against systemic candidiasis, as IL-17C-/- and IL-17RE-/- mice followed the same survival curve as littermate control mice." (PMID 25849644, 2015). "We therefore assessed the importance of IL-17C and IL-17RE in protection from systemic candidiasis by infecting mice in the tail vein with a standard dose of 2x105C." (PMID 25849644, 2015). "However, in another study, mice that lack IL-17C displayed an increased survival and attenuated kidney damage, although the fungal load was similar to the wild type, thus suggesting an immunopathological role for IL-17C during systemic Candida infection." (PMID 38407673, 2024). "Although the importance of IL-17RA/RC was clear, IL-17RA is used by other ligands including IL-17C, leaving open the possibility that cytokines in addition to IL-17A might contribute to immunity to candidiasis." (PMID 25849644, 2015). "Indeed, Il17c mRNA was strongly induced following Candida infection, in a manner similar to Il17a mRNA." (PMID 25849644, 2015). "Of the other IL-17 family members, we considered that IL-17C and its receptor IL-17RE were the most likely to be important in candidiasis, given the similarity of the IL-17A- and IL-17C-induced downstream gene profiles and their common propensity to act at mucosal surfaces." (PMID 25849644, 2015). "Therefore, it was surprising that IL-17C/IL-17RE signaling was dispensable for the three forms of candidiasis evaluated here." (PMID 25849644, 2015). "The induction of Il17c mRNA in the oral mucosa during OPC was the impetus for this study, but despite its induction at the mRNA level, mice lacking IL-17C were resistant to the forms of candidiasis tested including OPC." (PMID 25849644, 2015). "Surprisingly, however, we detected no role for the IL-17C/IL-17RE signaling axis in these forms of experimental candidiasis." (PMID 25849644, 2015).
co-infection (3 papers, 2019 to 2025). "TRANCE and IL-17C showed potential as a diagnostic signature indicating bacterial co-infection in the context of candidemia." (PMID 41229429, 2025). "The in vivo experiments show that co-infection causes the activation of the IL-17 signaling pathway and that the most abundant target proteins are IL-17C and C/EBPβ, resulting in the production of numerous inflammatory factors and chemokines." (PMID 31803158, 2019). "The three-protein logistic regression panel (LAP-TGF beta-1, TRANCE and IL-17C) differentiated cases with isolated candidemia from those with candidemia and bacterial co-infection [AUC 0.82; 95% CI 0.629–0.968]." (PMID 41229429, 2025). "TRANCE and IL-17C unexpectedly contributed to the model’s performance by indicating bacterial co-infection in the context of candidemia." (PMID 41229429, 2025). "QPCR analysis showed that the expression trend of 10 genes between the co-infection and control groups (IL-17C, NFκB, AP1, C/EBPβ, CXCL1, CXCL8, MMP1, MMP3, GM-CSF, and MUC5AC) was consistent with the RNA-seq results." (PMID 31803158, 2019). "Our research indicated that IL-17C as one of the IL-17-related cytokines and behaves actively in the lung co-infection model." (PMID 31803158, 2019). "The expression of IL-17C, CIKS, TRAF6, NFκB, C/EBPβ, and inflammatory chemokines were significantly up-regulated in response to co-infection." (PMID 31803158, 2019).
Psoriasiform dermatitis (3 papers, 2016 to 2025). A skin abnormality characterized by redness and irritation, with thick, red skin that displays flaky, silver-white patches (scales). "In addition, IL-17C is upregulated in murine psoriasiform dermatitis, and IL-17C-deficient mice develop milder skin inflammation upon imiquimod application." (PMID 30127781, 2018). "Other members of the IL-17 family, such as IL-17C and IL-17F, are expressed prominently in psoriasiform dermatitis, and they enhance innate defenses in epithelial cells." (PMID 40920623, 2025). "Conversely, selective overexpression of IL-17C in murine epidermis results in marked psoriasiform dermatitis." (PMID 30127781, 2018). "In addition, we observed enhanced mRNA expression of the interleukins Il17c, Il23 and Il33 which are key players in human psoriasiform dermatitis." (PMID 27050272, 2016). "However, it cannot be ruled out that basal keratinocytes could be the key drivers of inflammation through Il17c, as also suggested by recent findings in mouse and human psoriasiform dermatitis." (PMID 27050272, 2016).
Viral Infections (3 papers, 2020 to 2022). "In parallel, the viral infection also causes tissue damage (of lung, guts, etc.)that is repaired by IL-17C through induction of tight junction proteins, in combination with FGFs and TGF-α that would exert fibroblasts recruitment and proliferation to ultimately resulting in tissue repair." (PMID 35479098, 2022). "The upregulation of IL-17C during respiratory viral infection might be produced by epithelial cells upon virus infection which would explain the profile we observed in asymptomatic participants." (PMID 35479098, 2022). "While the upregulation of IL-17C during respiratory viral infection might be produced by epithelial cells upon virus infection the mechanisms for the downregulation of serum levels in Early Symptomatic participants are unclear." (PMID 35479098, 2022). "IL-17C is a cytokine described as pro-inflammatory and in combination with other mediators, works as an epithelial barrier against different bacterial and viral infections." (PMID 35479098, 2022). "Interleukin 17c (IL17c) and its receptor are present in the mouse olfactory mucosa, and the former is markedly upregulated upon poly I:C intranasal instillation, mimicking viral infection." (PMID 34835030, 2021). "Two studies investigated the role of IL-17C/RE in viral infections." (PMID 32174926, 2020).
acute pneumonia (2 papers, 2021 to 2022). "Prior studies showed a crucial role of IL-17C in the pathogenesis of immune-mediated skin diseases, autoimmune hepatitis, and acute pneumonia." (PMID 36420006, 2022).
Alzheimer disease (2 papers, 2024 to 2025). A progressive, neurodegenerative disease characterized by loss of function and death of nerve cells in several areas of the brain leading to loss of cognitive function such as memory and language. "IL-17C is up-regulated in several neurological diseases, such as Alzheimer’s disease, bipolar disorder, and stroke, but to the best of our knowledge, has not been previously reported in ASD." (PMID 40003312, 2025).
asthma (2 papers, 2020 to 2025). "Because of the functional overlap between IL-17A and IL-17C and the corresponding receptor complexes IL-17RA/IL-17RC and IL-17RA/IL-17RE, we examined the function of IL-17RE in mouse models of OVA-induced experimental asthma and acute exacerbation thereof." (PMID 32641167, 2020). "As it has been shown that IL-17A and IL-17C both require IL-17RA for the induction of inflammatory mediators in target cells and IL-17C promotes Th17 cell responses we hypothesized that the specific IL-17C receptor IL-17RE has a function in OVA-induced experimental asthma." (PMID 32641167, 2020).
autoimmune hepatitis (2 papers, 2020 to 2022). Hepatitis caused by autoantibodies. "IL-17RE is also highly expressed by liver resident CD4+ T cells and natural killer T cells and augments T cell function in autoimmune hepatitis together with IL-17C." (PMID 32641167, 2020).
breast carcinoma (2 papers, 2020). "Downregulation of IL-17C and its downstream cytokine IFNγ in breast cancer with a high level of ER expression indicates that IL-17C signaling transduction may also be associated with the regulation of ER." (PMID 33102239, 2020). "Since IL-17A, IL-17F, and IL-17C are initiators of IL-17 signal transduction, whereas IL-17E suppresses Th17 cell responses, ER downregulates IL-17 signal transduction in breast cancer by differentially regulating the expression of IL-17 cytokines." (PMID 33102239, 2020). "We found increased mRNA expression of Il17f, and a tendency toward an increase of Il17c and Il6, in the mammary tumors of HFD offspring." (PMID 32580156, 2020). "It was also noticed in our study that transcripts encoding IL-17A and IL-17F in the majority of samples and transcripts encoding IL-17C and IL-17E in half of the samples were absent according to TCGA Breast Cancer dataset, which made the quantitative analysis difficult." (PMID 33102239, 2020). "IL-17C is similar to IL-17A in promoting the expression of inflammatory cytokines and antibacterial peptides, whereas it is mainly derived from epithelial cells, which may explain why more positive samples with IL-17C expression were observed than those with IL-17A expression in breast cancer." (PMID 33102239, 2020).
chronic obstructive pulmonary disease (2 papers, 2022 to 2024). A chronic and progressive lung disorder characterized by the loss of elasticity of the bronchial tree and the air sacs, destruction of the air sacs wall, thickening of the bronchial wall, and mucous accumulation in the bronchial tree. "Moreover, IL-17C exacerbates chronic obstructive pulmonary disease (COPD) through neutrophil recruitment via upregulation of CXCL1." (PMID 38407673, 2024). "Specifically, pathogenic bacteria, such as influenza, increases epithelial IL-17C production in chronic obstructive pulmonary disease (COPD) patients, thus enhancing tumor growth through neutrophilic inflammation in the tumor microenvironment." (PMID 36358812, 2022).
depression (2 papers, 2020 to 2022). "IL-17, a pro-inflammatory cytokine, is a member of the cytokine family comprising IL-17A, IL-17B, IL-17C, IL-17D, IL-17E (IL-25) and IL-17F and it was found before, to be elevated in the serum of patients suffering from depression." (PMID 33322667, 2020).
experimental autoimmune encephalomyelitis (2 papers, 2015 to 2024). An autoimmune demyelinating disease of the central nervous system that is produced experimentally in animals by the injection of homogenized brain or spinal cord in Freund's adjuvant. "Knockout ACT1 (a key transcription factor for signals mediated by IL-17A, IL-17F, and IL-17C) reduced the number of infiltrating inflammatory cells and ameliorates experimental autoimmune encephalomyelitis." (PMID 37581321, 2024).
Hepatitis (2 papers, 2018). Inflammation of the liver. "Although we found increased IFN-γ mRNA level in the intestine and elevated IL-6 and IFN-γ serum levels in hosts receiving IL-17C−/− graft, decreased IL-6 and IFN-γ productions were detected in hepatitis with IL-17C deficiency." (PMID 30534126, 2018). "In the present study, we investigated the roles of IL-17C in T cell-dependent diseases such as contact dermatitis and hepatitis, T cell-independent diseases such as pulmonary fibrosis and inflammation, and endotoxin shock using Il17c−/− mice, which we newly generated." (PMID 30356086, 2018). "Taken all together, our observations indicate that IL-17C is not essential for development of T cell-dependent FITC- or DNFB-induced CHS or Con A-induced hepatitis." (PMID 30356086, 2018). "We demonstrated that Con A-induced hepatitis developed normally in Il17c−/− mice, indicating that IL-17C is not essential for that development." (PMID 30356086, 2018). "However, even when we used those authors’ experimental protocol, we found that Con A-induced hepatitis developed similarly in Il17c−/− mice to in wild-type mice (data not shown)." (PMID 30356086, 2018).
influenza (2 papers, 2020 to 2022). An acute viral infection of the respiratory tract, occurring in isolated cases, in epidemics, or in pandemics; it is caused by serologically different strains of viruses (influenzaviruses) designated A, B, and C, has a 3-day incubation period, and usually lasts for 3 to 10 days. "It was proposed that IL-17C would be able to boost IL-17A production to reinforce innate host barrier during influenza infection for example." (PMID 35479098, 2022). "Increased IL-17C expression in response to influenza was attenuated, but not abolished, in murine bronchial epithelial cells from IFNAR-/- and STAT-/- mice." (PMID 32232015, 2020). "Thus far, influenza, herpes simplex virus (HSV), and HRV have been shown to induce IL-17C gene and/or protein expression." (PMID 32232015, 2020).
leprosy (2 papers, 2013 to 2016). Leprosy is a chronic infectious disease affecting primarily the skin and peripheral nervous system. "That the IL-17 release was also influenced by the leprosy spectrum was indicated by BT patients who showed significant increase in expression of IL-17 isoforms: IL-17A (p<0.0002), IL-17C (p<0.003), IL-17D (p<0.003) and IL-17F (p<0.0001) as compared to the multibacillary LL patients." (PMID 23936569, 2013).
lung disease (2 papers, 2018 to 2024). "IL-17C was also involved in the immune response of respiratory epithelial cells: IL-17C heightened inflammatory responses of respiratory epithelial cells infected with Pseudomonas aeruginosa and was found in bronchial tissue of subjects with infection-related lung diseases." (PMID 38407673, 2024). "Il17c mRNA was constitutively expressed in the lungs of mice, and lung epithelial cells are known to produce IL-17C, suggesting that IL-17C may be involved in host defense via the lungs and/or in development of certain pulmonary diseases such as COPD and cystic fibrosis." (PMID 30356086, 2018). "Constitutive expression of Il17c mRNA was observed in the lungs from wild-type mice, but not Il17c−/− mice, suggesting that IL-17C may be involved in lung disease." (PMID 30356086, 2018).
Obesity (2 papers, 2017 to 2025). Accumulation of substantial excess body fat. "However, the exact role of IL-17C in obesity remains to be explored." (PMID 29132311, 2017).
pulmonary fibrosis (2 papers, 2018 to 2022). Chronic progressive interstitial lung disorder characterized by the replacement of the lung tissue by connective tissue, leading to progressive dyspnea, respiratory failure, or right heart failure. "Nevertheless, definitive evidence is yet to be provided, and the underlying mechanisms of action of IL-17C in regulating pulmonary fibrosis remain to be elucidated." (PMID 35550651, 2022). "All of these findings suggest that IL-17C might be a key cytokine in the pathogenesis of pulmonary fibrosis." (PMID 35550651, 2022). "Therefore, we investigated the role of IL-17C in bleomycin-induced pulmonary fibrosis, which develops independently of T cells." (PMID 30356086, 2018). "Thus, it was not essential for development of bleomycin-induced pulmonary fibrosis, although we expected IL-17C to contribute to development of T cell-independent IL-17A-mediated bleomycin-induced pulmonary fibrosis." (PMID 30356086, 2018). "Inflammation and fibrosis based on histological analysis (HE and EVG staining, respectively) were also comparable in the lungs of Il17c−/− and wild-type mice during bleomycin-induced pulmonary fibrosis, indicating that IL-17C is not essential for development of bleomycin-induced pulmonary fibrosis." (PMID 30356086, 2018).
Salmonella Infections (2 papers, 2021 to 2022). Infections with bacteria of the genus SALMONELLA. "HIO production of IL17C and its known downstream proinflammatory mediators, including CSF3 and DEF4BA, also suggest that IL17C signaling modulates human intestinal host defense against Salmonella infection." (PMID 34669717, 2021).
systemic fungal infection (2 papers, 2025). "Since 2016, due to its cooperation with other inflammatory cytokines, IL-17C has been regarded as a critical mediator and harmful amplifier of hyperinflammation, contributing to worse outcomes in systemic fungal infections." (PMID 41229429, 2025). "IL-17C, on the other hand, induces lethal inflammation by exacerbating the secretion of pro-inflammatory cytokines, thereby contributing to the development of systemic fungal infection." (PMID 40920877, 2025).
allergic rhinitis (1 paper, 2020). Inflammation of the nasal mucous membranes caused by an IgE-mediated response to external allergens. "The expression of IL-17C was evaluated by western blot and immunohistochemistry and compared between allergic rhinitis (AR) and control subjects." (PMID 33162788, 2020).
Allergy (1 paper, 2022). An allergy is an immune response or reaction to substances that are usually not harmful. "HVE inhibited the release of mediators involved in skin autoimmunity (IL-6 and IL-17C) and allergy (TSLP, IL-6, CCL26, and MMP-9) with a concentration-dependent fashion (IC50s < 25 μg/mL)." (PMID 36012541, 2022).
bacterial sepsis (1 paper, 2025). "In this model, the simultaneous upregulation of CXCL 10–11 and downregulation of IL-17C in isolated candidemia, suggests a more effective clearance and a less dysregulated immune response compared to bacterial sepsis." (PMID 41229429, 2025).